ADAM9 (ADAM metallopeptidase domain 9)
Diseases named in the same sentence as ADAM9 in open-access papers (continued):
Sharing a sentence is not in itself a finding about the gene and the disease.
metastatic melanoma (1 paper, 2013). A melanoma that has spread from its primary site to another anatomic site. "Soluble ADAM9, MMP7 and OPN, analyzed in the conditioned media from control and miR-transduced metastatic melanoma cells, confirmed their miR-126&126*-dependent reduction (right)." (PMID 23437250, 2013).
myeloid leukemia (1 paper, 2020). A clonal proliferation of myeloid cells and their precursors in the bone marrow, peripheral blood, and spleen. "ADAM9 was shown to be an important and specific factor for encephalomyocarditis virus (EMCV) entry, which was inhibited upon ADAM9 knockout in myeloid leukemia derived cells and HEK293T cells." (PMID 33392273, 2020).
neuropathy (1 paper, 2023). A disorder affecting the nervous system that manifests with pain, tingling, numbness, and/or muscle weakness. "Before pursuing in vivo experiments with our ADAM9-MSNs, we first assessed potential side effects using clinically relevant in vitro models for neuropathy and bone marrow toxicity." (PMID 37445886, 2023).
Nystagmus (1 paper, 2024). Rhythmic, involuntary oscillations of one or both eyes related to abnormality in fixation, conjugate gaze, or vestibular mechanisms. "This phenotype is more severe than the typical ADAM9-associated presentation, characterized by poor vision in childhood without nystagmus and photoaversion." (PMID 38892339, 2024). "We identified homozygosity for an unreported ADAM9 deletion encompassing exons 5 to 11 (26 to 40 kb in size) in a male evaluated at 9 months of age due to profound visual deficiency with nystagmus, indicative of LCA; however, ERG was not available for diagnosis." (PMID 38892339, 2024).
osteoarthritis (1 paper, 2023). A noninflammatory degenerative joint disease occurring chiefly in older persons, characterized by degeneration of the articular cartilage, hypertrophy of bone at the margins and changes in the synovial membrane. "Further analysis of these enriched pathways in injurious hydrostatic pressure highlighted differential expression of several genes known to be involved in osteoarthritis, such as Fgf2, Ep300, Ngf, Adam9, Igfbp3, Sox9, Comp, Col6a1, Col6a2 and Col11a1." (PMID 38144567, 2023). "In addition, several genes known to play a key role in progression of osteoarthritis (e.g., Fgf2, Ep300, Ngf, Adam9, Igfbp3, Sox9, Comp, Col6a1, Col6a2 and Col11a1) were modulated in our injurious hydrostatic pressure hip cap datasets, thereby validating this approach." (PMID 38144567, 2023).
ovarian clear cell cancer (1 paper, 2019). An invasive malignant neoplasm that arises from the ovary and is characterized by a predominance of clear and hobnail malignant epithelial cells. "However, in ovarian clear cell carcinoma cells, ADAM9 was found to rather impede rather than foster cell migration, possibly suggesting cell‐type specificity of ADAM9 involvement in cell migration." (PMID 30556643, 2019).
papillary renal cell carcinoma (1 paper, 2008). A rare subtype of renal cell carcinoma, arising from the renal tubular epithelium and showing a papillary growth pattern, which typically manifests with hematuria, flank pain, palpable abdominal mass or nonspecific symptoms, such as fatigue, weight loss or fever. "Interestingly, ADAM9 was also found in most (13 of 17) papillary renal cell carcinomas." (PMID 18582378, 2008).
Retinal dystrophy (1 paper, 2019). Retinal dystrophy is an abnormality of the retina associated with a hereditary process. "Likewise, mutations in canine Adam9 are responsible for the retinal dystrophy occurring in some Glen of Imaal terriers." (PMID 30914507, 2019).
rheumatoid arthritis (1 paper, 2025). A chronic, systemic autoimmune disorder characterized by inflammation in the synovial membranes and articular surfaces. "Immune pathways were also enriched: Role of Osteoclasts in Rheumatoid Arthritis (FDR = 5.88 × 10−3; MMP12, ADAM9, NFKBIA), T-cell receptor and Interleukin-1 signaling (both FDR = 8.83 × 10−3; NFKBIA, PSME3)." (PMID 41465234, 2025).
sarcoidosis (1 paper, 2021). Sarcoidosis is a multisystemic disorder of unknown cause characterized by the formation of immune granulomas in involved organs. "SARS-CoV2 ORF8 host targets belonging to the sarcoidosis gene panel (IL17RA, EMC1, PLD3, GDF15, FKBP10, ADAM9, and PLAT) highlight significant pathways related to sarcoidosis pathogenesis." (PMID 34440765, 2021).
Stroke (1 paper, 2023). Sudden impairment of blood flow to a part of the brain due to occlusion or rupture of an artery to the brain. "A locus in ADAM23 has been shown to correlate with stroke outcome, and in our study multiple ADAM gene family members such as ADAM9, ADAM17, ADAM19 were associated with poor stroke outcomes." (PMID 36691064, 2023).
systemic lupus erythematosus (1 paper, 2021). An autoimmune multi-organ disease typically associated with vasculopathy and autoantibody production. "Levels of ADAM9 are significantly elevated in T cells from patients with systemic lupus erythematosus, and thus, T‐cell activity may regulate ADAM9 expression." (PMID 34725916, 2021).
viral myocarditis (1 paper, 2024). Myocarditis that is caused by an infection with a viral agent. "In the present study, we used a well-established murine model of viral myocarditis to determine the role of ADAM9 in EMCV infection and subsequent development of virus-induced cardiac injury." (PMID 38755212, 2024). "Our findings identify a role for ADAM9 in the innate antiviral response, specifically MDA5-mediated IFN production, which protects against virus-induced cardiac damage, and provide a potential therapeutic target for treatment of viral myocarditis." (PMID 38755212, 2024).
tumor (144 papers, 2004 to 2026). "Among patients with mutant EGFR, carriers of the ADAM9 rs6474526 G allele (TG + GG) demonstrated a significantly increased risk of larger tumor sizes (OR = 2.939, 95% CI = 1.099–7.858; p = 0.025)." (PMID 40429751, 2025). "In a different approach, targeting ADAM9 with the novel antibody–drug conjugate IMGC936 has shown preclinical efficacy by causing cytotoxicity in ADAM9-positive tumour cell lines and potent antitumor activity in xenograft models." (PMID 40427200, 2025). "Second, while our study provides evidence of associations between ADAM9 SNPs, tumor size, and EGFR mutation frequency in LUAD patients, we lack survival data for the recruited cohort." (PMID 40429751, 2025). "ADAM9 and -17 expression have been associated with tumor grade and were proposed as potential diagnostic/prognostic biomarkers." (PMID 38306361, 2024). "ADAM9 overexpression in solid tumors is also associated with aggressive tumor phenotype and poor clinical prognosis." (PMID 39441449, 2024). "ADAM9 is a tumor-associated antigen highly expressed in many types of solid tumors and is involved in carcinogenesis and tumor progression, but the underlying mechanisms remain poorly understood." (PMID 35780836, 2022). "Our current work provides new insights into how ADAM9 regulates tumor-associated angiogenesis in a context-dependent manner." (PMID 34671207, 2021). "Using the Cancer Genome Atlas database, we found that higher expression of ADAM9 in tumor tissues was associated with poorer survival of HCC patients (log-rank p = 0.00039), while ADAM10 and ADAM17 exhibited no such association." (PMID 32245188, 2020). "ADAM9 overexpression is associated with high-grade and aggressive tumours, tumours with distant metastasis, poorly differentiated tumours and tumours that have a poor prognosis." (PMID 31030477, 2019). "Factors that showed a statistically significant association with ADAM9-positive expression were tumour size (adjusted odds ratio [adj." (PMID 31030477, 2019). "This biological function of ADAM9 is increased in cancer cells and is linked to promotion of tumor progression." (PMID 29118335, 2017). "From the ADAM9 IHC staining, we demonstrated high levels of ADAM9 are associated with blood vessel formation, suggesting ADAM9 promotes angiogenesis for tumor progression." (PMID 29118335, 2017). "● Deficiency of specific ADAMs such as ADAM9, 15 and 17 resulted in decreased growth of heterotopically injected tumour cells in mice models." (PMID 21906355, 2011). "In the χ2-tests higher ADAM9 protein expression was significantly associated tumour grade, distant metastasis, positive nodal status and papillary as well as chromophobe histologic subtype." (PMID 18582378, 2008). "In conclusion our results support the notion of ADAM9 to be associated with more aggressive tumours and unfavourable outcome." (PMID 18582378, 2008). "On protein level, ADAM9 was significantly associated with higher tumour grade, positive nodal status and distant metastasis." (PMID 18582378, 2008). "In renal cancer, ADAM9 is significantly overexpressed compared to adjacent normal tissue, and its expression is associated with a higher tumour grade, positive nodal status, and distant metastasis and correlates with reduced patient survival in univariate analysis." (PMID 40427200, 2025). "Specifically, platelet‐derived adhesion molecules such as P‐selectin, integrin α6β1, and integrin αIIbβ3 may engage tumor‐associated receptors such as PSGL‐1, CD44, ADAM9, and integrin αvβ3, ultimately promoting active internalization by tumor cells." (PMID 40788220, 2025). "Next, to clarify the effects of ADAM9 genetic polymorphisms on the clinicopathological status of PCa, we examined factors such as pathologic staging, pathologic Gleason grade groups, clinical staging, tumor invasion statuses, and D'Amico classification." (PMID 39628685, 2024).
tumor (continued). "Our results not only elucidate the mechanism underlying cooperation between primary PCa tumor cells and distal OBs, but also indicate that targeting the ADAM9/WISP-1 axis may interrupt the progression to metastatic disease." (PMID 36778124, 2023). "Consequently, ADAM9 expression was associated with a morphological desmoplastic reaction, thereby affecting cancer malignancy via tumor proliferation in CRC." (PMID 36572816, 2023). "Moreover, based on the IHC method, the authors report that ADAM9 expression is associated with poor tumour differentiation and a worse prognosis of PC patients." (PMID 35565436, 2022). "ADAM9 is linked with tumor progression in different types of cancer." (PMID 34671207, 2021). "This analysis was performed using micro-dissected peritumoral areas of tumors grown after three days from grafting, a time point at which we previously could detect the first differences in tumor growth in ADAM9 deficient mice as compared to control mice." (PMID 32906814, 2020). "Also, using the TCGA database, we found that higher expression of ADAM9 in HCC tumor tissues is associated with poor survival of HCC patients." (PMID 32245188, 2020). "Similarly, the high expression of stromal ANXA2 was significantly correlated with short disease-free survival and overall survival, while the high expression of ADAM9 was associated with poor tumor differentiation and short overall survival in PDAC patients." (PMID 30700038, 2019). "However, as outlined in the Introduction, the observed association of ADAM9 expression with angiogenesis is in line with other reports, including reports on non‐tumor systems." (PMID 30556643, 2019). "As an active protease, ADAM9 has been implicated in the processing of extracellular matrix components, which may facilitate tumor cell invasion." (PMID 30556643, 2019). "While ADAM9 has been implicated in tumor progression and prognosis of a variety of cancers, due, in part, to the role of metalloproteinases in cell migration and invasion, to date cell cycle analyses and modulation of cell cycle proteins have not been investigated in the context of ADAM9." (PMID 23342005, 2013). "Probably this might have been due to the strong association of ADAM9 expression with positive pM- status and higher tumour grade." (PMID 18582378, 2008). "In our study, the significant associations of ADAM9 with prognostically adverse conventional tumour parameters (positive nodal status, distant metastasis, residual tumour in the resection margins and higher tumour grade) are clearly in line with these findings." (PMID 18582378, 2008). "IL-4-induced M2 macrophages were evaluated for ADAM9 expression, tumor migration and invasion capacity, extracellular matrix (ECM) degradation, cytoskeletal remodeling, and spheroid destabilization." (PMID 41890767, 2026). "IL-4-induced M2 macrophages upregulated ADAM9 and significantly enhanced tumor migration and invasion." (PMID 41890767, 2026). "Pseudotime trajectory analysis linked ADAM9 expression to M2 macrophage differentiation, while cell-cell interaction studies revealed ADAM9-high M2 macrophages as key signaling hubs in the tumor microenvironment." (PMID 42266684, 2026). "Single-cell sequencing was performed to analyze the distribution of ADAM9 in tumor microenvironment." (PMID 42266684, 2026). "ERG signatures including ADAM9 not only precisely forecasted the survival outcomes and therapeutic responses of LUAD patients but also comprehensively uncovered the oncogenic role of ADAM9 in promoting tumor progression through multi-dimensional analysis." (PMID 42266684, 2026). "For example, various tumor cells express the counter‐receptor ADAM9 (a disintegrin and metalloproteinase 9) for platelet integrin α6β1 and bind to α6β1 to activate platelets." (PMID 40491968, 2025).
tumor (continued). "Consistent with our in vitro findings, IHC staining of HRH1, ADAM9, and vimentin in tumor tissues from SAS-shHRH1-injected mice indicated downregulation of these proteins compared to control mice." (PMID 40113769, 2025). "Spatial maps showed that their TAM to MES2-like interactions (e.g., GRN-TNFRSF1A and CD14/ADAM9/ADAM17-ITGB1) were maximally enriched within high-CNV tumor-core domains and diminished toward infiltrative margins." (PMID 41235227, 2025). "In summary, this is the first study to explore distinct allelic effects of ADAM9 SNPs in a Taiwanese population, highlighting their impacts on EGFR mutation frequency and tumor progression in LUAD." (PMID 40429751, 2025). "Evidence from in vitro, in vivo, and clinical studies showed that ADAM9 facilitates lung tumor cell proliferation, adhesion to vascular endothelial cells, anoikis resistance, cell migration, tumor angiogenesis, growth, and metastasis in xenograft models." (PMID 40429751, 2025). "The anti-ADAM9 antibody-drug conjugate (ADC) IMGC936 has demonstrated potent antitumor activity in ADAM9-positive tumor cells and xenograft models." (PMID 41383622, 2025). "Recent studies have revealed that ADAM9 promotes tumor progression by protecting KRAS from lysosomal degradation and reducing its interaction with plasminogen activator inhibitor-1 (PAI-1) and microtubule-associated protein 1 light chain 3 (LC3)." (PMID 41383622, 2025). "In LUAD, ADAM9 is notably overexpressed and was shown to promote tumor growth in xenograft models by regulating angiogenic factors such as vascular endothelial growth factor A, interleukin-8, and angiopoietin-2." (PMID 40429751, 2025). "In PDAC tumour cells, ADAM9 expression is elevated and correlates with poor tumour grading and vascular invasion." (PMID 40427200, 2025). "The EFFscore comprises three genes—ADAM9, P2RY6 and CD36—all of which have been closely associated with tumor progression." (PMID 41383622, 2025). "By lowering ADAM9 expression, miR-126 lowers Osteosarcoma cell motility and invasiveness, limiting the tumor’s spreading potential." (PMID 40429954, 2025). "For example, interactions have been observed between platelet GPVI and tumor galectin-3, platelet integrin α6β1 and tumor ADAM9, platelet CLEC-2 and tumor podoplanin, and platelet GPIIb/IIIa and tumor ανβ3." (PMID 39934930, 2025). "ADAM9 is overexpressed in several tumors and affects tumor progression through different mechanisms." (PMID 39898241, 2025). "Previous studies examined the anti-tumor effect of knockdown of total ADAM9 or sADAM9, but this study used the new technology of neutralizing antibodies for sADAM9." (PMID 38928352, 2024). "The small molecule drug CCL347, which targets ADAM9, can enhance the tumor-killing ability of NK cells, making it a promising new treatment for HCC." (PMID 39346916, 2024). "The most significant findings included the transcriptional upregulation of MMP1 (125-fold), ADAM28, MMP9, and ADAM9 (5.2-fold, 4.4-fold, and 4.2-fold upregulated) in tumor tissue compared to normal skin." (PMID 38891088, 2024). "Our analysis revealed that ADAM9 expression was significantly higher in tumor tissues compared to corresponding matched normal tissues." (PMID 39628685, 2024). "Directly binding to platelet α6β1, a disintegrin and a metalloprotease 9 (ADAM9) was identified as the major receptor of α6β1 and this interaction efficiently promoted platelet activation, tumor cell extravasation, and lung metastasis." (PMID 39114075, 2024). "The protein expression of ADAM9 in KIRC using immunohistochemistry revealed results consistent with that of qRT-PCR, wherein a significantly higher expression of ADAM9 in tumour tissues was confirmed." (PMID 37082201, 2023). "Higher ADAM9 levels were detected in clinical PCa tumor tissue compared with normal tissue specimens, while ADAM9 blockade suppressed PCa tumor growth and reduced the formation of distant metastasis in orthotopic PCa mouse models." (PMID 36778124, 2023).